FGF10 (fibroblast growth factor 10)
Description:
Plays an important role in the regulation of embryonic development, cell proliferation and cell differentiation. Required for normal branching morphogenesis. May play a role in wound healing.
Synonyms: LADD3
Tractability: Antibody: UniProt places it where antibodies can reach, with high confidence; its Gene Ontology location is reachable by antibodies, with high confidence; UniProt predicts a signal peptide or a membrane-spanning region.
Gene: Protein-coding gene on chromosome 5 (44,300,247 to 44,389,977, reverse strand). Ensembl gene ENSG00000070193.
Subcellular location: Secreted
Pathways (Reactome):
Signal Transduction: Downstream signaling of activated FGFR1; FGFR1b ligand binding and activation; FGFR2b ligand binding and activation; FGFRL1 modulation of FGFR1 signaling; FRS-mediated FGFR1 signaling; FRS-mediated FGFR2 signaling; Negative regulation of FGFR1 signaling; Negative regulation of FGFR2 signaling; PI-3K cascade:FGFR1; PI-3K cascade:FGFR2; PI3K Cascade; PI5P, PP2A and IER3 Regulate PI3K/AKT Signaling; PIP3 activates AKT signaling; Phospholipase C-mediated cascade: FGFR1; Phospholipase C-mediated cascade; FGFR2; RAF/MAP kinase cascade; SHC-mediated cascade:FGFR1; SHC-mediated cascade:FGFR2
Developmental Biology: Developmental Lineage of Mammary Stem Cells; Developmental Lineage of Multipotent Pancreatic Progenitor Cells; Regulation of gene expression in early pancreatic precursor cells
Disease: Activated point mutants of FGFR2; Constitutive Signaling by Aberrant PI3K in Cancer; Signaling by FGFR2 in disease
Gene Ontology:
Molecular function: chemoattractant activity; fibroblast growth factor receptor binding; growth factor activity; heparin binding; protein binding; type 2 fibroblast growth factor receptor binding
Biological process: actin cytoskeleton organization; branching morphogenesis of an epithelial tube; bud outgrowth involved in lung branching; epithelial cell proliferation; ERK1 and ERK2 cascade; fibroblast growth factor receptor signaling pathway; lacrimal gland development; lung epithelium development; lung saccule development; mesonephros development; metanephros development; positive chemotaxis; positive regulation of ATP-dependent activity; positive regulation of DNA repair; positive regulation of epithelial cell migration; positive regulation of epithelial cell proliferation; positive regulation of G1/S transition of mitotic cell cycle; positive regulation of hair follicle cell proliferation; positive regulation of keratinocyte migration; positive regulation of keratinocyte proliferation; positive regulation of lymphocyte proliferation; positive regulation of MAPK cascade; positive regulation of peptidyl-tyrosine phosphorylation; positive regulation of Ras protein signal transduction; positive regulation of urothelial cell proliferation; and 19 more
Cellular component: cell surface; extracellular region; nucleus; plasma membrane; cytoplasm
Genetic constraint (gnomAD): Loss-of-function variants: 1 observed, 17.75 expected, observed/expected ratio (o/e) 0.0563, 90% interval 0.019 to 0.27. The upper end of that interval is the gene's LOEUF score, 0.27, which puts it in group 1 of 6, group 1 being the genes least tolerant of losing a copy. Missense variants: 185 observed, 248.57 expected, observed/expected ratio (o/e) 0.74, 90% interval 0.66 to 0.84. Synonymous variants: 105 observed, 95.25 expected, observed/expected ratio (o/e) 1.1, 90% interval 0.94 to 1.3.
Homologues: Orthologues: chimpanzee FGF10 (100% identical), pig FGF10 (99% identical), guinea pig FGF10 (99% identical), macaque FGF10 (99% identical), rat Fgf10 (99% identical), rabbit FGF10 (99% identical), dog FGF10 (98% identical), mouse Fgf10 (94% identical), tropical clawed frog fgf10 (71% identical), zebrafish fgf10a (51% identical), zebrafish fgf10b (50% identical). Paralogues in human: FGF7 (42% identical), FGF22 (38% identical), FGF3 (38% identical), FGF20 (32% identical), FGF5 (32% identical), FGF9 (32% identical), FGF16 (30% identical), FGF6 (28% identical), FGF13 (28% identical), FGF11 (26% identical), FGF4 (26% identical), FGF18 (25% identical), and 9 more.
Diseases named in the same sentence as FGF10 in open-access papers:
FGF10 is named in the same sentence as 176 diseases in open-access papers, as found by Europe PMC text mining. Sharing a sentence is not in itself a finding about the gene and the disease. The quoted sentences say what the papers report.
breast cancer (31 papers, 2006 to 2026). A primary or metastatic malignant neoplasm involving the breast. "Further, several cancers can arise due to Fgf10 gene mutations or/and FGF10 overexpression, such as prostate cancer, breast cancer, cholangiocarcinoma, and gastric cancer." (PMID 39766329, 2024). "FGF10 expression increases if the rs10941679 SNP is present, which in turn would increase risk of breast cancer in patients expressing the FGFR2 SNP rs2981578 variant." (PMID 35193394, 2022). "FGF10 plays a role in promoting the occurrence and development of breast cancer mainly due to the following causes." (PMID 35668376, 2022). "Genetic variants near the FGF10 locus have been identified through genome-wide association studies and their detection is considered as a risk factor for breast cancer formation." (PMID 32676501, 2020). "Other genome-wide association studies of breast cancer predisposition identified variants on chromosome 5p12 some 274–317 kb distal to the fibroblast growth factor 10 (FGF10) that confer a risk, preferentially for estrogen receptor-positive breast tumors." (PMID 23527311, 2013). "FGF10 is amplified in approximately 10% of breast cancers, and possibly the observed risk variants influence FGF10 expression." (PMID 23527311, 2013). "Besides, variation near the FGF10 gene locus are genetic risk factors for the susceptibility of breast cancer and FGF10 is an oncogene of breast cancer." (PMID 35668376, 2022). "However, as yet, little is known about the mechanism by which FGFR2 and FGF10 mutations act as risk factors in predisposition to breast cancer." (PMID 23527311, 2013). "HCN1 is adjacent to other genes that may be related to breast cancer risk including FGF10 and MRPS30, and is just outside a region linked to mammographic density." (PMID 19232126, 2009). "Our finding that individuals in whom intrinsically higher levels of FGFR2 are expressed in their skin fibroblasts also have higher levels of FGF10 suggests that the increased breast cancer risk might be due to a stronger paracrine effect between stromal and tumor cells involving FGF10 signaling." (PMID 21767389, 2011). "For example, FGF7, FGF10, and FGF22 bind exclusively to FGFR2 IIIb, with FGFR2 IIIb/FGF10 being highly associated with breast cancer development." (PMID 39596875, 2024). "The EGFR pathway activated by EREG and the PI3K/Akt/mTOR pathway activated by FGF10 are well known to be part of the mechanisms of resistance to HER2-targeted therapy in HER2-positive breast cancer." (PMID 35954313, 2022). "FGF10 is also expressed exclusively by the stromal fibroblasts of normal and breast cancer tissue and has been reported to be an oncogene in mammary tumour virus mouse models and in a subset of breast carcinomas showing high expression of the protein." (PMID 35193394, 2022). "This interaction is lost during early-stage breast cancer and is controlled by paracrine signalling including FGF10/FGFR2b signalling and FGF20 signalling." (PMID 35193394, 2022). "FGF10 stimulation of the ER-positive breast cancer cell line MCF-7 decreases dependency on oestrogen and sensitivity to treatment with anti-oestrogen, suggesting that anti-FGF10/FGFR inhibitors can be used to bypass resistance to anti-hormone therapies." (PMID 35193394, 2022). "Altogether, these data highlight a role for TTP and RCP in FGFR2b trafficking and early signalling specifically induced by the recycling ligand FGF10 in breast cancer cells." (PMID 34086370, 2021). "High expression of FGF10 has been reported in about 10% of breast cancer and correlated with tumor progression." (PMID 34650974, 2021). "The breast cancer cell lines were treated with FGF7 or FGF10 for 1 or 8 min., and such early signalling was analysed using phosphoproteomics, hereafter referred to as trafficking phosphoproteomics approach 1 (TPA1)." (PMID 34086370, 2021). "In humans, FGF10 is expressed in both normal and breast cancer tissue, being detectable in 92% of the primary tumors." (PMID 32676501, 2020).
breast cancer (continued). "In vitro studies using breast cancer cell lines showed that FGF10 stimulation lead to the nuclear translocation of a 55 kDa C-terminal fragment of FGFR1, which in turn promoted the transcription of genes that stimulate cell migration and invasion." (PMID 30405704, 2018). "The minor g-allele of signal 1 SNP rs10941679 conferred a 15% increased risk of ER+ breast cancer and higher expression levels of the MRPS30 and FGF10 genes and was the most strongly associated SNP with MRPS30 expression in this 1 Mb region." (PMID 27640304, 2016). "We also performed MLPA analysis to detect copy number variations in FGFR2 and FGF10 in breast tissue of 50 sporadic breast cancer patients." (PMID 23527311, 2013). "A mouse mammary tumor virus (MMTV) insertional mutagenesis screen for genes associated with mammary cancer also identified FGFR2 and FGF10." (PMID 23300950, 2013). "Our results suggest that the increased breast cancer risk associated with SNP rs2981578 is due to increased FGFR2 signaling activity in stromal fibroblasts, possibly also involving paracrine FGF10 signaling." (PMID 21767389, 2011). "Since FGF-10 upregulation has been implicated in breast cancer, we used MDA-MB-231 and MCF-7 breast cancer cell lines as models in which to overexpress recombinant PEA3." (PMID 19410332, 2009). "Increased levels of FGF10 are observed in ~10% of human breast cancers, and amplification and overexpression of several FGFRs, including FGFR1, FGFR2, and FGFR4, have been observed in breast cancers." (PMID 16933995, 2006). "If these roles of FGF10 on adipocytes are confirmed in breast adipocytes, this may open novel avenues to explore in the context of how cells in the breast cancer microenvironment (e.g., adipocytes) affect tumorigenesis." (PMID 41131959, 2026). "Indeed, FGF10 is overexpressed in breast cancer and signals through its receptor FGFR2b in breast cancer epithelial cells." (PMID 41131959, 2026). "FGF10 was preincubated at 37 °C for up to 24 h before being added to MCF7 breast cancer cells." (PMID 40257501, 2025). "Additionally, FGF10 stimulates the migration and invasion of pancreatic cancer cells and contributes to the development of breast cancer." (PMID 38342791, 2024). "In conclusion, FGF7 and FGF10 in the breast cancer microenvironment might regulate FGFR2 signalling-dependent breast cancer cell behaviour through complementary molecular mechanisms." (PMID 35193394, 2022). "FGF7 and FGF10 are among the components of breast cancer organoid growth medium, indicating that they both play a crucial role in the initiation and/or maintenance of breast cancer." (PMID 35193394, 2022). "However, the significant increase in the transcription level of FGF10 was observed in about 10% of breast cancer patients." (PMID 35668376, 2022). "FGF10 stimulation of the breast cancer cell line MCF-7 [a cell line described as estrogen receptor-positive (ERpos)] drive the cells to a basal-like cancer phenotype with diminished dependency to estrogen associated with decreased sensitivity to treatments with anti-estrogen." (PMID 32676501, 2020). "Interestingly, some breast carcinoma cell lines show high expression of FGF10, supporting the possible role of autocrine FGF10 signaling in human breast cancer progression." (PMID 32676501, 2020). "Supporting the paracrine nature of FGF10 signaling described during early mammary gland development FGF10 expression in normal and breast cancer tissue is limited to the stromal fibroblasts- Luminal epithelial cells of the normal human breast duct do not express FGF10." (PMID 32676501, 2020). "However, in 10% of the breast carcinomas displaying a high epithelial/stroma ratio, FGF10 is ectopically expressed in the epithelium at high level." (PMID 32676501, 2020).
breast cancer (continued). "IL-6, VEGF, and TGF-β1 have been proved to be commonly overexpressed in human breast cancer cases, FGF10 played the important role in type III epithelial-mesenchymal transition (EMT) on breast cancer cells and initiation of metastasis, and high expression of FGF17 causes tamoxifen resistance." (PMID 29581982, 2018). "Analysis of FGFR2b signaling networks in vitro revealed that stimulation of FGFR2b with FGF10 promoted receptor recycling and led to an increase in breast cancer migration, whilst stimulation of FGFR2b with FGF7 resulted in receptor degradation and led to increased cell proliferation." (PMID 30405704, 2018). "Breast cancer EMT has been studied using fibroblast growth factor-10 (FGF-10)." (PMID 26828526, 2016). "Thus, PEA3 can regulate the transcription of Fgf-10 and such modulation can control breast cancer cell behaviour." (PMID 19410332, 2009). "Thus, we have identified PEA3 as a negative regulator of Fgf-10 expression in a murine cell line and confirmed that activity also is seen in human breast cancer cell lines (MCF-7 and MDA-MB-231)." (PMID 19410332, 2009). "In the present study, we speculate that the inhibitory role of PEA3 on breast cancer cell migration could be due to the reduction of Fgf-10 expression by negative regulation through PEA3." (PMID 19410332, 2009). "Based on above information, we speculated that FGF10 and VEGFA might play an essential role in the screening and clinical intervention for second primary lung cancer of high-risk breast cancer patients, but further investigation should be conducted to verify this conjecture." (PMID 35668376, 2022). "Thus, above findings suggest that FGF10 may be one of the characteristic genes of lung adenocarcinoma patients with breast cancer." (PMID 35668376, 2022). "Furthermore, the mutations of TRIM73, DLX6 and CNGB1 and high expression of FGF10 and VEGFA might play an important role in the development of lung adenocarcinoma in breast cancer patients." (PMID 35668376, 2022). "Finally, the regulatory subunit of phosphatidylinositol 4,5-bisphosphate 3-kinase (PI3K) p85 which is known to be indirectly recruited to FGFR via the FRS2/GRB2/GAB1 complex, has been shown to bind to phosphorylated Y734 on FGFR2b upon FGF10 stimulation in epithelial breast cancer cells." (PMID 30405705, 2018). "These genes included BPTF, PHF5A, and SPG7 in cancer of female genital organs, as well as FGF10, NFIX, and SCAP in breast cancer." (PMID 38409266, 2024). "A possible explanation for this resistance is offered by the copy number gain of FGF3 and FGF10 in this cell line, both of which have previously been defined as resistance mechanisms to BYL719 in breast cancer." (PMID 34663790, 2021). "In fact, both SConES GS and GM selected chromosome regions related to breast cancer, like 3p24 (SLC4A7/NEK10), 5p12 (FGF10, MRPS30), 10q26 (FGFR2), and 16q12 (TOX3)." (PMID 33735170, 2021). "Therefore, Fgf10 plays pleiotropic roles in both mammary gland development, homeostasis and cancer and elucidating its mechanism of action and cellular targets will be crucial to either enhance mammary gland development or to find innovative targets to treat aggressive breast cancer." (PMID 32676501, 2020). "FGF10 promotes tumor invasion and metastasis by binding to FGFR2 in pancreatic cancer and breast cancer cell lines." (PMID 33034614, 2020). "Our previous study showed that FGF-10 is effective in EMT induction through the alteration of epithelial and mesenchymal markers in breast cancer cell lines." (PMID 31611737, 2019). "Our previous study has shown that FGF-10 plays a key role in type III EMT on MCF-7 and MDA-MB231 breast cancer cell lines." (PMID 31611737, 2019). "These assays showed that the PRE containing SNP1 frequently interacted with the FGF10 and MRPS30 promoter regions in MCF7 and BT474 breast cancer cell lines, but only with MRPS30 in the MDA-MB-361, MDA-MB-231, and Bre80 cell lines." (PMID 27640304, 2016).
breast cancer (continued). "FGF10 is an oncogene that binds to FGFR2 and is overexpressed in ∼10% of human breast cancers, whereas MRPS30 plays a key role in apoptosis." (PMID 27640304, 2016). "FGF7 and FGF10 bind the epithelial b isoforms of FGFR1 and 2, with FGF7 being more specific for FGFR2b; they are potent mitogens that play crucial roles, among others, in wound healing, development, and cancer, including breast cancer." (PMID 41131959, 2026). "Additionally, the reported role in breast cancer of fetal mammary developmental genes, such as TBX3, WNT-10b, FGF10, and LEF1, highlights their potential clinical relevance as biomarkers and therapeutic targets." (PMID 40001874, 2025). "However, it is still not clear about the effects of endocrine therapy and chemotherapy on the expression levels of FGF10 and VEGFA in breast cancer patients, which is also one of the important directions of our next research." (PMID 35668376, 2022). "FGF10 regulates Epithelial to Mesenchymal Transition (EMT), cell viability, migration and colony formation in breast cancer cell lines by increasing the expression of mesenchymal factors (such as vimentin, N-cadherin, snail, slug, TGF-β), and ERK1/2 and PI3K–AKT signalling." (PMID 35193394, 2022). "Mouse models of mammary carcinogenesis have long established the FGF signalling pathway as a major contributor to tumorigenesis, and a mouse mammary tumor virus (MMTV) insertional mutagenesis screen for genes involved in breast cancer has identified both FGFR2 and FGF10." (PMID 23527311, 2013). "We also performed MLPA analysis to detect copy number variations in FGFR2 and FGF10 in sporadic breast cancer patients but did not identify any copy number changes in either of the two genes." (PMID 23527311, 2013). "Indeed, FGF10, a member of the canonical FGF7 subfamily of proteins, is elevated in highly vascularized invasive subcutaneous mice mammary tumors and several human breast cancer subtypes (both Luminal A and TNBC)." (PMID 40001874, 2025). "Therefore, according to the results of all GO and KEGG analyses, FGF10 and VEGFA might play an important role in the development of second primary lung cancer in breast cancer patients." (PMID 35668376, 2022). "Furthermore, FGF10, but not TGFα, required FGFR activation to induce EGFR_T693 phosphorylation and ERK activation in breast cancer cells expressing endogenous FGFR2b." (PMID 34086370, 2021).